FAP (fibroblast activation protein alpha)
Diseases named in the same sentence as FAP in open-access papers (continued):
Sharing a sentence is not in itself a finding about the gene and the disease.
tumor (continued). "Numerous preclinical and animal studies have previously demonstrated that FAP-expressing stroma is a critical component of the TME that inhibit antitumor immunity and depleting FAP+ stroma suppresses tumor growth and restores antitumor immunity." (PMID 39035007, 2024). "Another group demonstrated that TGF-β1-activated CAFs enhance tumor invasion, pulmonary metastasis, and EMT by autophagy and the overexpression of FAP-α." (PMID 38455762, 2024). "Fibroblast activation protein (FAP), a membrane-bound protease, targeted by CAR-T cells, effectively enhances the killing of tumor cells in vitro and is considered a suitable target for CAR-T cell therapy against immune-suppressive TME components." (PMID 38690275, 2024). "By analyzing scRNA-seq data from 11 organs, we observed a progressive increase in the proportions of FAP+ CAFs and DAB2+ TAMs in normal (n = 25), adjacent (n = 60), and tumor (n = 220) samples." (PMID 39239526, 2024). "By ablating FAP+ stromal cells and matrix, FAP-CAR T cells overcome these barriers and thereby successfully extravasate into tumors, eventually infiltrate into tumor nests, and retain their functionality." (PMID 37607999, 2023). "In another mouse 4T1 metastatic BC model, researchers developed a FAP-targeting immunotoxin αFAP-PE38 to deplete FAP-positive stromal cells, which showed efficacy in suppressing tumor growth." (PMID 37784082, 2023). "Some preclinical studies of FAP-CAR-T cells have been conducted for various solid cancers, such as lung and pancreatic cancers, showing increased homing and a more robust anti-tumor response." (PMID 36853475, 2023). "In tumor lesions containing MYH11+αSMA+ CAF and FAP+αSMA+ CAF, the density of CD3+ or CD8+ T cells was remarkably reduced compared to T cell-permissive CAFs, indicating that both CAFs were associated with T cell exclusion." (PMID 37784082, 2023). "FAP remodels the extracellular matrix (ECM) and promotes immunosuppression, thus limiting the ability of CAR-T cells to infiltrate the tumor." (PMID 36853475, 2023). "The aim of the study was to evaluate the tumor-targeting characteristics of radiolabeled FAPI multimers in vitro and in vivo, thereby providing information for the design of FAP-targeted radiopharmaceuticals based on the polyvalency principle." (PMID 37321827, 2023). "Studies have shown that targeting CAR-T cells to fibroblast activation protein (FAP) can remove stromal cells, and engineering CAR-T cells secreting Heparinase enzyme (HPSE) can degrade the tumor matrix thereby overcoming tissue barriers." (PMID 36717905, 2023). "In THCA tumor, CTLA4 (rho = 0.691), HAVCR2 (rho = 0.610), TIGIT (rho = 0.641), VTCN1 (rho = 0.618) showed remarkably positive with FAP expression." (PMID 37166418, 2023). "Depletion of FAP-expressing CAF cells by CAR-T cells enhanced intra-tumoral CD8+ T cells and FN-γ production significantly impeding tumor growth." (PMID 38022679, 2023). "In this study, we show three mechanisms that contribute to the efficacy of FAP-CAR T cells, compared to TAA-targeted mesothelin (Meso)-CAR T cells, in inhibiting tumor growth." (PMID 37607999, 2023). "In this study, we found that several CAF-related markers, including PDGFR-β, α-SMA, FAP-α, S100A4/FSP1, collagen type I, and Twist1, were expressed at high levels in stromal CAFs in the proximity of tumor areas in BMs." (PMID 36860926, 2023). "In contrast, FAP is considered to play an important role in fibroblast growth, tissue remodeling of the ECM, epithelial carcinogenesis, tumor growth (proliferation) and angiogenesis in malignant tissue." (PMID 36980775, 2023). "They will enable imaging of lesions expressing FAP, PSMA, or both on the tumor cell surface or within the TME for the theranostic management of heterogeneous tumors." (PMID 37046676, 2023).
tumor (continued). "Although HHLA2 and FAP are expected to be associated with anti-tumor immune response, we could not verify whether the expression of HHLA2 and FAP affects the efficacy of immune checkpoint inhibitors, because only a few cases used immune checkpoint inhibitors in this study." (PMID 36598731, 2023). "Another study evaluated an oral DNA vaccine targeting FAP in BALB/c mice transplanted with CT26 colon carcinoma cells after vaccination on days 3 and 10 after tumor injection." (PMID 37316886, 2023). "Immunization with rAd‐FAP/hlivin α‐transduced DCs suppressed LLC volume and improved the survival of tumor‐bearing mice." (PMID 37773704, 2023). "This study provides proof-of-concept of FAP-targeted PDT in PDAC, and future studies should demonstrate the feasibility in other tumour types and the effects on tumour growth, immunomodulation, and efficacy of other systemic therapies." (PMID 37408254, 2023). "tumor and ascitic fluid were positive for CD44, and weak expression of CAFs (PDGFRα, FAP) was observed." (PMID 37958844, 2023). "FAP elevation has been reported to contribute to cell proliferation, the EMT process, angiogenesis, and immunosuppression, thereby promoting tumor progression." (PMID 37490719, 2023). "Overexpression of FAP can activate the FAP-STAT3 pathway that drives the expression of CCL2, upregulating the recruitment of MDSCs into the TME, further promoting tumour development." (PMID 39935547, 2023). "Accordingly, 4662 tumor-bearing syngeneic mice were first treated with MigR, Meso-CAR or FAP-CAR T cells." (PMID 37607999, 2023). "Comparison of FAP expression among different STS entities is limited considering the small sample size within each STS entity cohort ranging between 7 and 30 tumor samples each." (PMID 37727209, 2023). "It was shown that when FAP-specific CAR-T cells were used alongside a tumor antigen-specific CAR, an enhanced anti-tumor activity in A549 lung cancer cells was observed." (PMID 37328876, 2023). "Wherein, in BLCA tumor, CSF1R (rho = 0.706), HAVCR2 (rho = 0.686), IL-10 (rho = 0.682), and PDCD1LG2 (rho = 0.753) showed the strongest positive correlation with FAP expression." (PMID 37166418, 2023). "Using a coimplantation model, the researchers revealed that FAP+ CAFs were indispensable for fostering MDSC recruitment and tumor growth, and importantly, FAP overexpression was sufficient to equip normal fibroblasts with tumor-promoting abilities." (PMID 36708970, 2023). "Therefore, there might be unspecific and off-target uptake of quinoline-based tracers, which can increase the background uptake level and lower the image contrast, thus interfering the identification of FAP-positive tumor lesions and even leading to false diagnoses." (PMID 36986548, 2023). "A distinct expression pattern of PDGFR-β, S100A4/FSP1, FAP-α, α-SMA, and collagen type I in the stromal CAFs was observed in relation to the tumor area." (PMID 36860926, 2023). "Recently, 68Ga-labeled quinoline-based FAP inhibitor (FAPI) has allowed for the imaging of tumor stroma by targeting FAP, among which [68Ga]FAPI-04 has exhibited favorable tumor-to-background ratio (TBR) and kinetics." (PMID 36522509, 2023). "Treatment of pancreatic CAFs with all-trans retinoic acid (ATRA) reduces expression of αSMA and FAP, decreases the production of ECM, reduces the expression and secretion of IL-6, and results in CAF-mediated reduction of migration and EMT in the tumor cells." (PMID 37046676, 2023). "Prior studies have shown that FAP-CAR T cell therapy in human LC xenografts and homologous mouse PC models can reduce tumor vascular density, restrain desmoplasia, and grow native PC." (PMID 37784082, 2023). "They observed immune control only after depleting FAP+CAFs, which were responsible for overexpression of CXCL12 that restricted recruitment of T cells into the tumor site." (PMID 38313431, 2023).
tumor (continued). "Targeting FAP and a TAA will enhance the anti-tumour effects of the CAR-T cell through dampening down the immunosuppressive TME." (PMID 39935547, 2023). "Several other OVs armed with BiTE, such as FAP and EGFR, have proved to enhance T-cell activation and accumulation in the tumor site, resulting in higher anti-tumor efficacy." (PMID 37631987, 2023). "Overexpression of FAP and integrins αvβ3 on tumor cells is the main factor by which [68Ga]Ga-FAPI-RGD shows high uptake in tumor and metastatic lesions." (PMID 37284441, 2023). "Alternatively, stromal depletion was possibly maintained by the persistent activity of FAP UCAR T-cells, which were still detectable in the tumor 3 weeks post infusion." (PMID 37251405, 2023). "In GC tumour tissue sections, there were fibroblast-like cells with double-positive for POSTN and FAP staining according to IF." (PMID 37199594, 2023). "Although the tumor burden was diminished under SoC treatment, the mRNA expression levels of SPARC and FAP were unaffected in corresponding samples of the treatment groups compared to vehicle-treated controls." (PMID 38136299, 2023). "DCs present antigens from eNVs-FAP, which activate antigen-specific CD8+ T cells to kill FAP+CAFs and tumor cells." (PMID 37553810, 2023). "Binary logistic regression analysis revealed that tumor location, PCA, and FAP were independent predictors for discriminating GHA from GA." (PMID 37538113, 2023). "CAF markers, which mainly consist of fibroblast activation protein (FAP), α-smooth muscle actin (α-SMA), and Vimentin, promote tumor progression 9-11." (PMID 36632455, 2023). "In the crosstalk between tumor cells and TME, FAP expressing CAF play a key role in carcinogenesis and metastatic spread." (PMID 37614665, 2023). "In this way, FAP fosters changes in ECM architecture, culminating in increased ECM permissiveness and facilitating tumor invasiveness." (PMID 38313431, 2023). "Another study showed that a monoclonal antibody named RG7386, capable of simultaneously targeting FAP and DR5, had significant anti-tumor activities." (PMID 37316886, 2023). "An in vitro analysis of the tumor sections revealed homogenous staining by IL2-7NP2-TNFmut, confirming the cellular expression of human FAP similar to the staining observed with 7NP2 in an IgG1 format." (PMID 37092450, 2023). "In immunotherapy with DNA vaccines, in vivo studies showed that vaccination against FAP triggers the host's immune response against the tumor, increases the penetration of CD8+ T cells into the TME, and reduces tumor growth." (PMID 37316886, 2023). "In addition, they concluded that the uptake of [18F]FAPI-42 could reflect the level of FAP expression, and it was independent of tumor size, degree of enhancement, type of gene mutation, and targeted therapy as compared to [18F]FDG." (PMID 37763225, 2023). "This is why several studies have shown that the more FAP is produced in TME, the more aggressive the tumor is, and the poorer the prognosis." (PMID 37892020, 2023). "BGN and FAP were also positively correlated with advanced TNM, poor tumor differentiation, LNM, and postoperative PM according to the 8th edition of the AJCC Cancer Staging Manual." (PMID 36632455, 2023). "Real-time 2-photon microscopy confirmed that the first treatment of FAP-CAR T cells rendered tumors permissive to Meso-CAR T cells allowing their extravasation, infiltration of and function within tumor nests." (PMID 37607999, 2023). "With regards to sarcomas, in humanized NOD-scid IL2Rγnull mice inoculated with human fibrosarcoma cells expressing FAP, the combination of anti-FAP-F19-ΔCD28/CD3ζ-CAR-T cells and PD-1 blockade demonstrated significant anti-tumor activity and improved survival." (PMID 37333052, 2023). "TGFβ-activated CAFs promote tumor invasion, pulmonary metastasis, and EMT, acting particularly through overexpression of FAP." (PMID 37509656, 2023).
tumor (continued). "Immunohistochemistry analysis of metastatic nodules demonstrated marked mitigation of the FAP+, α‐SMA+, DESMIN+, PDGFRα+, and PDGFRβ+ fibrotic components in TGF‐βR1‐treated Bmal1−/− tumor‐bearing mice." (PMID 37330661, 2023). "The data above indicates that the combination of FAP- and Meso-CAR T cells enhanced the anti-tumor activity of Meso-CAR T cells." (PMID 37607999, 2023). "After the FAP-mBBZ CAR-T treatment, the ratio of MDSCs among all immune cells in tumor tissue was significantly decreased in PANC02-A2 models." (PMID 37046312, 2023). "As a result, FAP-positive CAF acts as a major cell source of C-C motif chemokine ligand 2 (CCL2), which enhances immunosuppression through tumor- and inflammation-promoting myeloid-derived suppressor cells (MDSCs)." (PMID 38313431, 2023). "Western blot assay in Panc02 tumor-derived primary CAFs further validated that LY reversed TGF-β1-induced expression of α-SMA, fibronectin and FAP, and consequently inactivated pSmad2/3." (PMID 37328484, 2023). "The FAP mRNA levels showed a significant positive correlation with the ACTA2, COL11A1, TNC, and PDPN genes in PanCK(-) AOIs at EOCC tumor invasive margin." (PMID 37964075, 2023). "Those in the sequential group (FAP + CLDN18.2) received the prior FAP-mBBZ CAR-T cells on day 10, and CLDN18.2-mBBZ CAR-T cells were subsequently infused on day 18 after tumor cell inoculation." (PMID 37046312, 2023). "[68Ga]Ga-SB04028 demonstrated >1.5-fold higher tumor uptake (10.1 ± 0.42 %ID/g) than [68Ga]Ga-PNT6555 (6.38 ± 0.45 %ID/g) and concordant with the findings from FAP inhibition assays where natGa-SB04028 was realized to be more potent than natGa-PNT6555." (PMID 37375746, 2023). "More type of tumors with high FAP expressed should be used for validation of 99mTc-HYNIC-FAPI-04 SPECT imaging, such as the tumor model co-cultured with tumor matrix." (PMID 36986521, 2023). "FAP was correlated with decreased density of CD8 + T cells (Spearman’s rho – 0.32, p < 0.001) and immunosuppressive tumor microenvironment (TME) status." (PMID 35951090, 2023). "We sought to determine how the upregulation of FGF20, a downstream effector of WNT signaling in FAP(+) CAFs, can potentially influence neighbor PanCK(+) tumor epithelial cells at EOCC tumor invasive margin." (PMID 37964075, 2023). "Second, we found that FAP-CAR T cells disrupted immune-exclusion by depleting the stromal cells and matrix-dense network surrounding tumor nests that deter T cell penetration of the stromal border and prevent their direct contact with tumor cells." (PMID 37607999, 2023). "In contrast, significant correlations were found for FAP, vimentin, CAIX, CD68 and CD44, thus indicating that tumoroids are able to retain the inter-tumor heterogeneity present in the tumor tissues." (PMID 37736770, 2023). "In a preclinical mouse model of PDAC, it was demonstrated that CAFs that express the fibroblast activation protein (FAP) within the ECM produce and secrete CXCL12, which in turn binds to the PDAC tumor cells, coating them." (PMID 37284199, 2023). "Generally, the expression patterns of FAPα and DPP4 in the organs overlap very little, with the exception of invading fibroblasts and some tumor cells." (PMID 38136590, 2023). "Although several novel FAP-targeting radiotherapeutic agents have been developed, such as [90Y]Y-FAPI-04, [177Lu]Lu-DOTA.SA.FAPi, and [177Lu]Lu-FAPI-46, their tumor-retention time and efficacy in clinical investigation have been disappointing." (PMID 36770755, 2023). "Future functional characterization is warranted to demonstrate the intercellular crosstalk between FAP(+) CAFs producing FGF20 and tumor epithelial cells having enhanced FGFR2 protein levels at the tumor invasive margin of EOCC." (PMID 37964075, 2023).
tumor (continued). "In conclusion, the present study suggests that injection with rAd‐FAP/hlivin α‐transduced DCs promotes immune‐enhanced TEM by killing CAFs and suppresses tumor growth, thereby prolonging mouse survival, which is an advancement in the field of tumor immunology." (PMID 37773704, 2023). "The synergy we observed between FAP-CAR T cells given in combination with Meso-CAR T cells or anti-PD-1 can, at least in part, be explained by changes in the immune landscape of the tumor microenvironment, as well as their impact on systemic immunity." (PMID 37607999, 2023). "Once again, FAP(hF1) UCAR T-cells successfully accumulated in the orthotopic TNBC tumors and promoted subsequent Meso2 UCAR T-cell tumor infiltration and activity." (PMID 37251405, 2023). "In a preclinical model, FAP-targeted radiotherapy enhanced anti-PD-1-mediated TGI by modulating the TME and increasing the recruitment of tumor-infiltrating CD8+ T cells." (PMID 37086273, 2023). "[68Ga]Ga-AV02070 containing a pyridine-4-carbonyl moiety has better binding affinity and tumor uptake than [68Ga]Ga-AV02053 containing a pyridine-3-carbonyl moiety, making it a promising candidate for the design of FAP-targeted tracers." (PMID 36986548, 2023). "FAP participates in epithelial–mesenchymal transition (EMT) in malignant tumors, promotes the invasion and migration of tumor cells, and ultimately promotes tumor metastasis, which indicates that CAFs play an important role in the development of tumors." (PMID 36675506, 2023). "Furthermore, the results of DEGs and HALLMARK GSEA analysis showed that the FAP high expression was significantly correlated with EMT, cell junction, IL-6/STAT3, and TGF-β signaling pathway and chemokine releasing, which further suggests its immune suppressive role and close interaction with tumor." (PMID 37046312, 2023). "Based on the previous significant differences in the expression levels of the two subtypes of C1 and C2 immune checkpoints, we further investigated the correlation between COL10A1/FAP/FN1 and tumor immune checkpoints." (PMID 38063927, 2023). "However, this association was not noted when FAP expression was high in the tumor margin." (PMID 37316886, 2023). "[68Ga]Ga-SB03045 and [68Ga]Ga-SB03058 were evaluated for their FAP-targeting capabilities using substrate-based in vitro binding assays, and in PET/CT imaging and ex vivo biodistribution studies in an HEK293T:hFAP tumor xenograft mouse model." (PMID 37110717, 2023). "Conversely, developing CAR T-cells engineered to target fibroblast-activation protein (FAP), although promotes CAR T-cells trafficking, they induce significant off-tumor toxicities owing to high FAP expression in healthy tissues." (PMID 37020537, 2023). "This phenotype can be reversed by inhibiting the enzymatic activity of FAPα during matrix formation, which leads to the disorganization of the ECM and prevents tumor invasion." (PMID 38136590, 2023). "Our comprehensive specialized CAF multiplex panel which used protein-based detection consisted of most commonly used markers for CAF: Alpha-SMA, FAP, S100 and Thy-1 with CD45 and Pan CK to identify hematopoietic cells and tumor cells respectively." (PMID 38192631, 2023). "This control release system significantly reduced CAF marker expression, such as α-SMA, FAP-α, and TGF-β levels and further inhibited tumor growth." (PMID 37627173, 2023). "In contrast, we detected many GFP+ FAP-CAR T cells infiltrating into the tumors, which diminished both FAP+ stromal cells and PanCK+ tumor cells, further validating the robust anti-tumor activity of FAP-CAR T cells in this autochthonous PDAC model." (PMID 37607999, 2023). "Depleting fibroblastic STAT3 or CCL2, or murine CCR2 attenuated the FAP-induced MDSC infiltration and tumor-promoting effects in vivo." (PMID 36708970, 2023). "By targeting FAP, FBP can inhibit the function of both TAMs and cancer cells, leading to a reduction in tumor growth and metastasis." (PMID 37601380, 2023).